ZBP1 (Z-DNA binding protein 1)
Diseases named in the same sentence as ZBP1 in open-access papers (continued):
Sharing a sentence is not in itself a finding about the gene and the disease.
COVID-19 (continued). "Moreover, ZBP1 was also identified among the ISGs up-regulated in CI patients with COVID-19." (PMID 35587515, 2022). "The use of IFN therapy in patients infected with SARS-CoV-2 would therefore mimic the increased and sustained ZBP1 expression observed in the critically ill patients with COVID-19, which could result in multi-organ damage, cytokine storm and mortality in patients." (PMID 35587515, 2022). "Moreover, patients with progressive COVID-19, who succumbed to infection, had increased ZBP1 expression in their immune cells, particularly NK cells, CD4+ memory and naïve T cells, effector memory CD8+ T cells and B memory and naïve cells, compared with patients with stable COVID-19." (PMID 35587515, 2022). "The fold-change expression of MDA5 (P = 0.0006), ZBP1 (P <0.0001), and AIM2 (P = 0.0004) in the nasopharyngeal epithelial cells from all COVID-19 patients was significantly higher than the healthy control group." (PMID 38714196, 2024). "Several IFN-related genes, such as SPATS2L, OAS2, ISG15, ZBP1, and IFI44L, exhibited similar patterns of upregulation across both dengue and COVID-19 datasets, while others, such as AIM2 and RTP4, showed distinct regulation." (PMID 38444851, 2024). "In a pattern similar to that of ZBP1 mRNA expression, the expression of AIM2 in nasopharyngeal epithelial cells was significantly higher than PBMC samples of COVID-19 patients with mild disease (P = 0.03)." (PMID 38714196, 2024). "The potential therapeutic value of targeting PANoptosis in inflammatory diseases has also been recently assessed against severe COVID-19 given that SARS-CoV-2 increases RIPK1 activation and ZBP-1 expression to promote viral spread." (PMID 37409125, 2023). "In this study, we investigated the ZBP1, AIM2, and MDA5 expression levels in COVID-19 patients with different intensities of the disease." (PMID 36320810, 2022). "We observed that the expression of ZBP1 was significantly increased in neutrophils, dendritic cells, macrophages, basophils, NK cells, CD4+ T cells and Treg cells from patients with COVID-19 compared with healthy controls." (PMID 35587515, 2022). "The expression levels of ZBP1 (P=0.001), AIM2 (P=0.001), and MDA5 (P= 0.003) transcript were significantly higher in COVID-19 patients than the control group." (PMID 36320810, 2022). "The results also revealed that the expression levels of ZBP1, AIM2, and MDA5 were significantly higher in the critical and severe COVID-19 patients compared to those with mild disease (P<0.05)." (PMID 36320810, 2022). "This study examined expression of key viral nucleic acid sensor genes MDA5, ZBP1, and AIM2 in nasopharyngeal epithelial cells and peripheral blood mononuclear cells (PBMCs) obtained from 153 COVID-19 patients across a spectrum of disease severity (mild, severe, and critical) and 42 healthy controls." (PMID 38714196, 2024). "This study aimed to address two specific knowledge gaps: 1) How do expression patterns of critical viral sensor genes (MDA5, ZBP1, and AIM2) differ between immune cell populations (peripheral blood mononuclear cells [PBMCs]) and airway epithelial tissue in COVID-19 patients?" (PMID 38714196, 2024). "Our research shows that male COVID-19 patients exhibit increased expression of AIM2 and ZBP1 genes, which could be a crucial factor in the sex-specific immune reactions in this disease." (PMID 38714196, 2024). "Molecularly, ADAR1 has been shown to suppress ZBP1-mediated PANoptosis, but the role of ADAR1 in COVID-19 remains unknown." (PMID 36419185, 2022). "Our aim in this study was to measure the level of MDA5, ZBP1, and AMI2 mRNA in the nasopharyngeal epithelial cells as well as PBMCs of COVID-19 at different stages of disease to assess the role of these PRR in the antiviral response and the inflammatory settings of COVID-19 patients." (PMID 38714196, 2024).
COVID-19 (continued). "Additionally, single cell transcriptomic analysis showed that ZBP1 was more abundantly expressed in immune cells from patients who succumbed to COVID-19 than in those who recovered without the need for hospitalization." (PMID 35587515, 2022). "Therefore, inhibiting ZBP1 activity may improve the efficacy of IFN therapy, paving the way for the development of new and critically needed therapeutics for COVID-19 as well as other infections and inflammatory conditions where IFN-mediated cell death and pathology occur." (PMID 35587515, 2022). "Patients who succumb to COVID-19 infection have higher expression of ZBP1 in their immune cells compared to non-hospitalized patients with stable COVID-19, further suggesting that there may be a pathological role for ZBP1 in driving COVID-19 severity during IFN therapy." (PMID 36419185, 2022).
Sepsis (15 papers, 2019 to 2026). Sepsis is defined as life-threatening organ dysfunction caused by a dysregulated host response to infection. "Loss of ZBP1 in macrophages protects heart against sepsis‐induced myocardial dysfunction and inflammatory cell infiltration." (PMID 40289345, 2025). "Zbp1 deficiency significantly enhanced the survival rate of mice in the cecal ligation and puncture‐induced sepsis model." (PMID 40289345, 2025). "Our findings reinforce these studies by emphasizing the significance of ZBP1 in the inflammatory response and cell death mechanisms associated with sepsis." (PMID 39465383, 2024). "Utilizing the in vivo CLP model, we found that the deficiency of Zbp1 and Ripk3 attenuated the severity of sepsis-induced ALI." (PMID 39465383, 2024). "This supports the pathogenic role of ZBP1 in sepsis-induced inflammation and organ failure." (PMID 41392977, 2025). "Importantly, ZBP1 elevation reversed the protective function of LL-37 in lung injury in sepsis-caused ALI mice." (PMID 40559884, 2025). "Together, the current study highlights that LL-37 can ameliorate the progression of ALI caused by sepsis in in vitro and in vivo models by suppressing oxidative injury and the inflammatory response, concomitant with ZBP1 down-regulation and autophagy activation." (PMID 40559884, 2025). "Fifthly, while we corroborated the critical role of ZBP1 in NUFIP1-mediated ribophagy associated with CD4+ T lymphocytes’ PANoptosis in sepsis, the precise interactional dynamics and underlying molecular mechanisms between these proteins remain to be elucidated." (PMID 40995563, 2025). "Combined loss of myeloid-specific Atg16l1 and Zbp1 accelerates LPS-mediated sepsis in mice." (PMID 31287416, 2019). "Prior scRNA‐seq findings revealed significant upregulation of ZBP1, XAF1, IFI44L and SOCS1 in B cells from sepsis patients that exhibit increased susceptibility to PANoptosis." (PMID 40600354, 2026). "In summary, ECG protects sepsis induced ALI mice by inhibiting necroptosis mediated by the ZBP1/MLKL/RIPK1 signaling pathway." (PMID 41496909, 2025). "In sepsis-induced ALI, Z-DNA-binding protein 1 (ZBP1) deficiency in macrophages mitigates mitochondrial damage, consequently reducing macrophage pyroptosis mediated by NLRP3 inflammasome activation." (PMID 40028334, 2025). "This investigation partially elucidates the potential mechanism by which ZBP1-PANoptosome modulates the activation of the cGAS-STING pathway in the setting of sepsis." (PMID 40995563, 2025). "Immunohistochemical staining further confirmed that NDI reduced ZBP1 expression in pulmonary endothelial cells in sepsis." (PMID 41392977, 2025). "Here, we present evidences that ZBP1 plays a dominant role in LPS‐induced M1 macrophage polarisation and sepsis‐induced myocardial dysfunction." (PMID 40289345, 2025). "We found that, compared with the sham and DLL4– neutrophils/sepsis groups, the DLL4+ neutrophils/sepsis group had significantly higher ZBP1 mRNA and protein expression, whereas NDI effectively decreased ZBP1 expression." (PMID 41392977, 2025). "Previous study shows that ZBP1 deficiency protects against organ injury and improves survival in the CLP sepsis model." (PMID 41392977, 2025). "How exactly does LL-37 reduce inflammation and oxidative stress injury in sepsis-induced ALI via ZBP1-mediated autophagy?" (PMID 40559884, 2025). "Survival analysis in the sepsis-induced ALI demonstrated that Zbp1−/− mice had a markedly higher survival rate compared to WT mice." (PMID 39465383, 2024). "This dysfunction was significantly reduced in Zbp1−/− mice, highlighting the pivotal role of ZBP1 in the progression of mitochondrial-mediated cell death during sepsis." (PMID 39465383, 2024). "Critically, during sepsis, internalized eCIRP in PVECs disrupts the interaction between ZBP1 and TRIM32, impeding proteasomal degradation of ZBP1 while stabilizing it." (PMID 39465383, 2024).
Sepsis (continued). "To elucidate the role of ZBP1 in the pathogenesis of sepsis-induced ALI in vivo, we administered rmCIRP intravenously alongside a non-lethal dose of LPS via intratracheal instillation in mice." (PMID 39465383, 2024). "Taken together, these results demonstrate that ZBP1-mediated PANoptosis contributes to pathology and mortality associated with sepsis-induced ALI, highlighting the significance of ZBP1 in the pathogenesis of this disease." (PMID 39465383, 2024). "Unexpectedly, combined deletion of Atg16l1 and Zbp1 accelerated LPS-mediated necroptosis and sepsis in mice." (PMID 31287416, 2019). "Consequently, it is challenging to distinguish between the role of ZBP1 in LPS‐induced sepsis and its recognition of contaminating DNA." (PMID 40289345, 2025). "The top ten differentially expressed genes in this study include Gm29879, Lcn2, Cxcl10, Zbp1, Lbhd2, C5aR1, Cxcl10, Lbhd2, Cxcl9, and Fpr1, all of which might play a role in the pathophysiology of sepsis-induced WMI." (PMID 41584453, 2025). "However, the elevation of ZBP1 cannot completely block the protective efficacy of LL-37 against sepsis-induced ALI." (PMID 40559884, 2025). "snRNA‐seq data indicated that macrophage‐derived ZBP1 could potentially be crucial in myocardial dysfunction induced by sepsis." (PMID 40289345, 2025). "IP results demonstrated an increase in ZBP1 polyubiquitination levels upon LPS stimulation, while the addition of eCIRP significantly reduced the LPS-induced polyubiquitination of ZBP1 by Ub-TRIM32, underscoring eCIRP’s inhibitory effect on ZBP1 ubiquitination during sepsis." (PMID 39465383, 2024). "Given its pivotal role in these processes, we hypothesized that ZBP1 might also play a significant role in PANoptosis of PVECs in response to LPS and eCIRP during sepsis-induced inflammation." (PMID 39465383, 2024). "Moreover, ZBP1-mediated elevation of autophagy may account for the protective efficacy of LL-37 against sepsis-induced ALI." (PMID 40559884, 2025). "However, whether ZBP1 and M1 macrophage polarisation it mediates participate in sepsis‐induced myocardial dysfunction remains unclear." (PMID 40289345, 2025). "Since Zbp1 deletion enhanced TRIF-mediated necroptosis in Atg16l1-cKO BMDMs ex vivo, we asked whether loss of Atg16l1 and Zbp1 in myeloid cells would further exacerbate LPS-mediated sepsis." (PMID 31287416, 2019). "Prior scRNA‐seq data showed pronounced upregulation of ZBP1, XAF1, IFI44L and SOCS1 in B cells from sepsis patients that displayed heightened PANoptosis sensitivity." (PMID 40600354, 2026). "In sepsis, DLL4+ neutrophils increase in the blood and lungs, upregulating ZBP1, cleaved gasdermin D, cleaved caspase-3, and phosphorylated MLKL, all of which are markers of PANoptosis, exacerbating ALI." (PMID 41392977, 2025). "This stabilization of ZBP1 enhances the ZBP1-receptor-interacting protein kinase 3 (RIPK3)-dependent PANoptosis in PVECs, thereby exacerbating the severity of post-sepsis ALI136." (PMID 40860191, 2025). "Our observations in sepsis-induced MPVEC death further support this model, highlighting the versatility of ZBP1 in engaging diverse cell death pathways." (PMID 39465383, 2024). "C57BL/6 wild type (WT), Casp8−/−, Ripk3−/−, and Zbp1−/− mice were subjected to the cecal ligation and puncture (CLP) sepsis model." (PMID 39465383, 2024). "Intriguingly, in the context of sepsis, eCIRP impedes the interaction between TRIM32 and ZBP1, suppresses TRIM32-mediated polyubiquitination and proteasomal degradation of ZBP1, and thereby stabilizes its expression." (PMID 39465383, 2024). "We found that the levels of NUFIP1 and ZBP1 in the CD4+ T lymphocytes of septic patients significantly increased compared to those without sepsis, corresponding to experimental data in murine models, thereby underscoring their conserved biomarker potential for the diagnosis of sepsis." (PMID 40995563, 2025).
Sepsis (continued). "Our research results demonstrate that ECG alleviates sepsis-induced ALI by inhibiting the NLRP3/Caspase-1/GSDMD signaling pathway-mediated pyroptosis, the Bcl-2/Bax/Caspase-3 signaling pathway-mediated apoptosis, and regulating the ZBP1/MLKL/RIPK1 signaling pathway-mediated necroptosis." (PMID 41496909, 2025). "Additionally, ZBP1, XAF1, IFI44L, SOCS1, and PARP14 were notably high in HighPANscore cells, aligning with our observations of upregulated expression of IFI44, IFIH1, IFIT1, IFIT2, and RSAD2 in lung tissues from sepsis-induced animal models." (PMID 38239341, 2023).
acute pancreatitis (11 papers, 2021 to 2026). An acute inflammatory process that leads to necrosis of the pancreatic parenchyma. "While ZBP1’s role in promoting cell pyroptosis has been reported in acute pancreatitis mouse models, its correlation with hepatocyte pyroptosis in ALF has not been explored until now." (PMID 40614007, 2025). "These tsRNAs influence the progression of pancreatic cancer and acute pancreatitis by modulating various pathways, including ZBP1/NLRP3, Hippo, PI3K/AKT, glycolysis/gluconeogenesis, and Wnt signaling." (PMID 39896345, 2025). "Three targeted genes, Btg2, Zbp1, and Cd44, indirectly support the association between PAITA and tRF3-Thr-AGT in the mechanisms underlying acute pancreatitis initiation." (PMID 35045793, 2022). "Moreover, the uncontrolled expression of ZBP1 and following ZBP1-dependent pyroptosis are the main reason for acute pancreatitis (AP)." (PMID 36142136, 2022). "Notably, genetic ablation of ZBP1 abolishes PANoptosis, impairing viral clearance, while inflammatory injury in acute pancreatitis and the pathological process of spinal cord injury can be significantly improved by inhibiting ZBP1- PANoptosome-mediated PANoptosis." (PMID 40721869, 2025). "Sensing host-derived nucleic acid ligands causes the spontaneous activation of ZBP1, that is responsible for many auto-inflammatory diseases, such as perinatal lethality, inflammatory bowel disease (IBD), heatstroke and oxidative stress-induced injuries, and acute pancreatitis (AP)." (PMID 36142136, 2022).
colorectal cancer (8 papers, 2020 to 2025). A primary or metastatic malignant neoplasm that affects the colon or rectum. "Adar1 knockout mice are resistant to the development of colorectal cancer, which can be reversed by deletion of the Zα2 domain of ZBP1." (PMID 38069556, 2023). "Notably, ZBP1-mediated PANoptosis contributes to the toxic side effects in healthy tissues of colorectal cancer patients under DNA-damage therapies, suggesting ZBP1 can be a promising therapeutic target to alleviate chemotherapy-related side effects." (PMID 40721869, 2025). "Furthermore, in colorectal cancer patients, dsRNA is induced by chemotherapy and sensed by ZBP1 in normal colonic tissues, suggesting ZBP1-mediated PANoptosis is activated by chemotherapy in normal tissues." (PMID 39465258, 2024). "ZBP1 agonists are not yet available, but ZBP1 may be self-activated in inflammatory settings, e.g., in IBD-associated colorectal carcinoma." (PMID 40422233, 2025).
colitis (6 papers, 2021 to 2026). Inflammation of the colon. "By mutating RHIM of RIPK1 in mice, Z-DNA-binding protein 1 (ZBP-1) could trigger necroptosis and induce perinatal lethality, skin inflammation, and colitis." (PMID 34867386, 2021). "Furthermore, mice with downregulated SETDB1 expression in intestinal stem cells develop spontaneous terminal ileitis and colitis by triggering Z-DNA-binding protein 1 (ZBP1)-dependent necroptosis via de-silencing endogenous retroviruses." (PMID 38057834, 2023). "Sensing of endogenous Z-DNA by ZBP1 has been shown to induce skin inflammation in mice with epidermis-specific RIPK1 knockout and colitis in mice with intestinal epithelial-specific FADD knockout." (PMID 41488643, 2025). "ZBP1-driven necroptosis contributes to the death of Casp8−/−Ripk1−/− mice at birth, and TNFR1 and ZBP1 contribute to ileitis and colitis in mice lacking caspase-8 in intestinal epithelial cells." (PMID 38548850, 2024). "The increased colonic inflammation and the resistance to colitis were restored by dual inactivation of RIPK3 and FADD, but not by inhibition of RIPK3, MLKL, or ZBP1 alone." (PMID 34462571, 2022).
colon cancer (5 papers, 2021 to 2025). "The ZBP1 gene is often expressed at higher levels in colon cancer cells and colon cancer, especially in situations involving inflammation like colitis-associated cancer." (PMID 40422233, 2025). "The expression of ZBP1 may activate the PANoptosome by enlisting more adaptors, hence affecting the progression of colon cancer." (PMID 40422233, 2025). "Although the pivotal role of ZBP1 in LGG has not been reported before, ZBP1 expression was found to be significantly up-modulated in ovarian and colon cancer and linked to poor prognosis." (PMID 36186436, 2022).
glioma (5 papers, 2023 to 2025). A benign or malignant brain and spinal cord tumor that arises from glial cells (astrocytes, oligodendrocytes, ependymal cells). "Miao proposed in his letter that ZBP1, a marker of cuproptosis‐related genes and necrotic apoptosis‐related genes, could be used as a risk score for predicting the prognosis of low‐grade glioma patients." (PMID 39936900, 2025). "Compared with normal tissues, except for MEFV, NLRP6, NLRP9, RIPK3, and ZBP1, the expression levels of the remaining genes were relatively high in glioma tissues." (PMID 37501725, 2023). "Additionally, DNA methylation analysis demonstrated that the promoter methylation levels of AIM2, CASP1, CASP8, NLRP3, and ZBP1 are significantly lower in gliomas than in non-tumor brain tissues." (PMID 39901195, 2025).
systemic lupus erythematosus (5 papers, 2022 to 2026). An autoimmune multi-organ disease typically associated with vasculopathy and autoantibody production. "Notably, ZBP1 deficiency phenocopies blocking cGAS-STING pathway-mediated autoimmune pathology exacerbation in pristane-induced lupus-like mice, underscoring its context-dependent roles in lupus pathogenesis." (PMID 41773721, 2026). "ZBP1 is an important cell apoptosis regulator in the occurrence and progression of systemic lupus erythematosus." (PMID 41562058, 2025). "In addition, ZBP1 was found to be highly expressed in patients with systemic lupus erythematosus, and significantly correlated with immune cell infiltration in patients`specimens suggesting its potential role on triggering autoinflammatory conditions." (PMID 36490282, 2022).
apical periodontitis (4 papers, 2022 to 2025). "In this study, Fusobacterium nucleatum (F. nucleatum) infection caused periapical inflammation through proinflammatory cell death and ZBP1 was involved in regulating the inflammatory activities caused by F. nucleatum infection in apical periodontitis (AP)." (PMID 36539813, 2022). "Fusobacterium nucleatum has also been reported to activate ZBP1, triggering inflammation in murine models of apical periodontitis." (PMID 40612110, 2025). "In addition, Fusobacterium nucleatum (F. nucleatum) can induce apical periodontitis by triggering pro-inflammatory cell death through Z-DNA binding protein 1 (ZBP1)." (PMID 39555084, 2024).